NUDT4 (nudix hydrolase 4)
Description:
Cleaves the beta-phosphate from diphosphoinositol polyphosphates such as PP-InsP5 (diphosphoinositol pentakisphosphate), PP-InsP4 (diphosphoinositol tetrakisphosphate) and [PP]2-InsP4 (bisdiphosphoinositol tetrakisphosphate), suggesting that it may play a role in signal transduction. Diadenosine polyphosphates, particularly Ap6A (P(1),P(6)-bis(5a-adenosyl) hexaphosphate) and Ap5A (P(1),P(5)-bis(5'-adenosyl) pentaphosphate) are downstream effectors of a signaling cascade that regulates cardiac KATP channels, can also be substrates, although with lower preference than the diphosphoinositol polyphosphates. Can also catalyze the hydrolysis of 5-phosphoribose 1-diphosphate, generating the glycolytic activator ribose 1,5-bisphosphate. Does not play a role in U8 snoRNA decapping activity (By similarity). Binds U8 snoRNA (By similarity).
Synonyms: DIPP2; KIAA0487; HDCMB47P; DIPP2alpha; DIPP2beta; DIPP-2B
Tractability: Small molecule: a structure with a bound ligand is known. PROTAC: ubiquitination databases record sites on it; its protein half-life has been measured.
Target class: Enzyme; Hydrolase
Gene: Protein-coding gene on chromosome 12 (93,377,883 to 93,408,146, forward strand). Ensembl gene ENSG00000173598.
Subcellular location: Cytoplasm
Subcellular location (Human Protein Atlas): Cytosol
Pathways (Reactome):
Metabolism: Synthesis of pyrophosphates in the cytosol
Gene Ontology:
Molecular function: diphosphoinositol-polyphosphate diphosphatase activity; protein binding; 5'-(N(7)-methylguanosine 5'-triphospho)-[mRNA] hydrolase activity; bis(5'-adenosyl)-hexaphosphatase activity; bis(5'-adenosyl)-pentaphosphatase activity; endopolyphosphatase activity; snoRNA binding; hydrolase activity; inositol-3,5-bisdiphosphate-2,3,4,6-tetrakisphosphate 5-diphosphatase activity; inositol-5-diphosphate-1,2,3,4,6-pentakisphosphate diphosphatase activity; inositol-5-diphosphate-1,3,4,6-tetrakisphosphate diphosphatase activity; pyrophosphatase activity
Biological process: adenosine 5'-(hexahydrogen pentaphosphate) catabolic process; calcium-mediated signaling; diadenosine hexaphosphate catabolic process; diadenosine pentaphosphate catabolic process; diphosphoinositol polyphosphate metabolic process; intracellular signal transduction
Cellular component: cytosol; nucleus; cytoplasm
Genetic constraint (gnomAD): Loss-of-function variants: 0 observed, 0.79 expected, observed/expected ratio (o/e) 0, 90% interval 0 to 1.78. That is too few expected variants to judge how well the gene tolerates losing a copy. Missense variants: 3 observed, 2.87 expected, observed/expected ratio (o/e) 1.04, 90% interval 0.44 to 1.87. Synonymous variants: 1 observed, 0.55 expected, observed/expected ratio (o/e) 1.83, 90% interval 0.34 to 1.92.
Homologues: Orthologues: chimpanzee NUDT4 (100% identical), macaque NUDT4 (99% identical), dog NUDT4 (98% identical), mouse Nudt4 (96% identical), rat Nudt4 (95% identical), tropical clawed frog nudt4 (78% identical), zebrafish nudt4a (77% identical), zebrafish nudt4b (74% identical), Drosophila melanogaster Aps (53% identical). Paralogues in human: NUDT4B (100% identical), NUDT11 (82% identical), NUDT10 (82% identical), NUDT3 (73% identical).
Diseases named in the same sentence as NUDT4 in open-access papers:
NUDT4 is named in the same sentence as 17 diseases in open-access papers, as found by Europe PMC text mining. Sharing a sentence is not in itself a finding about the gene and the disease. The quoted sentences say what the papers report.
breast carcinoma (1 paper, 2021). "Further investigation into the role of NUDT4, 13, and 21 in breast cancer progression may represent an interesting line of investigation in the future." (PMID 33668737, 2021).
diabetes (1 paper, 2017). "Up-regulation in diabetes compared to healthy and down-regulation following treatment in diabetes was observed for 5 genes: NUDT4, GSMT5, predicted NUBPL, predicted RGD1306157 and LOC362480." (PMID 28727746, 2017).
emphysema (1 paper, 2025). "We also found increased expression NUDT4, which has been recently identified as a marker of lymph node LECs in the lungs of emphysema patients with autoreactive TLOs compared with those with COPD without emphysema." (PMID 39437762, 2025).
gastric cancer (1 paper, 2022). A primary or metastatic malignant neoplasm involving the stomach. "Studies have shown that NUDT4 can be used as a prognostic target related to m7G methylation in gastric cancer, and the prognosis model based on this can better predict the prognosis of gastric cancer patients." (PMID 36506322, 2022).
hepatocellular carcinoma (1 paper, 2025). A malignant tumor that arises from hepatocytes. "Although EIF4E, EIF4G3, NUDT4, and NUDT11 expression levels did not exhibit a statistically significant differential between neoplastic and normal samples, their expression displayed an upward trend in hepatocellular carcinoma (HCC) tissues." (PMID 40485623, 2025).
liver cancer (1 paper, 2023). An epithelial or non-epithelial malignant neoplasm that arises from the liver. "Among the genes associated with the prognosis of liver cancer, the genes associated with shorter survival period are AGO2, DCPS, IFIT5, LARP1, NCBP2, NUDT10, and NUDT16; the genes associated with longevity are EIF4E3, EIF4G3, METTL1, NCBP1, NSUN2, NUDT11, NUDT4, and WDR4." (PMID 36845384, 2023).
lung carcinoma (1 paper, 2022). "It has been reported that NUDT4 is a prognostic biomarker in gastric cancer, but its role in lung cancer is also largely unknown." (PMID 36761423, 2022). "The m7G modification protein NUDT4 may be a novel biomarker in promoting the progression of lung cancer." (PMID 36761423, 2022). "NUDT4 was an independent risk factor in lung cancer patients, and there is no research exploring its function in lung cancer." (PMID 36761423, 2022). "There is no research studying the potential function of NUDT4 in lung cancer until now, and we observed its capability in promoting cancer cell proliferation but not cell migration according to our Transwell results." (PMID 36761423, 2022).
pancreatic cancer (1 paper, 2025). "In pancreatic cancer, circCGNL1 enhances the interaction of the phosphatase NUDT4 and histone deacetylase 4 (HDAC4), promoting HDAC4 dephosphorylation and nuclear translocation to modulate gene expression." (PMID 41049614, 2025).
Sepsis (1 paper, 2022). Sepsis is defined as life-threatening organ dysfunction caused by a dysregulated host response to infection. "Finally, we screened out two genes that were significantly associated with sepsis prognosis, NUDT4 and PARN." (PMID 36506322, 2022). "In addition, we identified two potential therapeutic targets for sepsis, namely NUDT4 and PARN, both of which are closely related to the prognosis of sepsis patients." (PMID 36506322, 2022). "The results showed that the expression of NUDT4 was significantly increased in sepsis patients." (PMID 36506322, 2022). "Finally, we screened the key genes in sepsis by WGCNA analysis, namely NUDT4 and PARN, and verified their expression patterns in sepsis in the datasets GSE131761 and GSE65682." (PMID 36506322, 2022). "However, there is a lack of relevant research on NUDT4 in infectious diseases and even sepsis." (PMID 36506322, 2022).
tumor (13 papers, 2010 to 2025). "Through pseudo-time analysis, we identified genes such as NCBP2, EIF3D, and NUDT4 boost the occurrence and development of malignant tumor epithelial cells, providing guidance for identifying potential therapeutic targets for CRC." (PMID 41406096, 2025). "Research in other cancer types has also indicated that NUDT4 downregulation affects tumor cell proliferation by impacting the m7G gene." (PMID 37968670, 2023). "Then, to explore its function in tumor cells, we designed shRNAs, sgRNAs, and overexpression plasmids to knock down, knock out, or overexpress NUDT4 expression." (PMID 36761423, 2022). "But when we compared immunochemistry results, the NUDT4 was found to be expressed more in tumor chips than normal tissue chips." (PMID 36761423, 2022). "Among the seven cell types with NUDT4 expression, there is a significant difference in epithelial cells between tumor and normal samples but varies in different patients." (PMID 36761423, 2022). "How NUDT4 affects tumor proliferation and what pathway is involved in this phenomenon need further exploration." (PMID 36761423, 2022). "Contrary to the long amplification of chromosome 7, the deletion on the same chromosome carried by a different tumour was short, with only two genes (Nudt4 and Ac1-114) mapping in this region." (PMID 20459814, 2010). "Most tumor cells expressed NCBP2, EIF3D, and NUDT4 suggesting that m7G-related genes may play a significant role in tumor development." (PMID 41406096, 2025). "Moreover, more apoptotic tumor cells occurred in NUDT4 knockdown groups in DAPI staining assay and apoptotic body were observed via TEM." (PMID 38297362, 2024). "Increasing NUDT4 expression has been related to the resistance of tumor cells to everolimus." (PMID 37089261, 2023). "In paired patients’ samples, NUDT4 was highly expressed in tumor epithelial cells of six patients." (PMID 36761423, 2022). "Then, the CCK8 assay and Transwell assay were conducted to observe the cell functions, which showed that overexpression of the NUDT4 promoted cell proliferation capabilities in both cell lines, but the migration capabilities of the tumor cells were still untouched." (PMID 36761423, 2022). "In contrast, overexpressing NUDT4 promoted tumor cell proliferation." (PMID 36761423, 2022). "On the other hand, we found that NUDT4 might be a novel target inhibiting tumor cell proliferation." (PMID 36761423, 2022). "An elevated protein expression of EIF4E, EIF4G3, LARP1, METTL1, NCBP1, NUDT4, and NUDT11 was discerned in the carcinoma samples, whereas the WDR4 expression was comparable between the tumor and adjacent non‐tumorous tissues." (PMID 40485623, 2025). "Correspondingly, there were some genes that were part of the CAP formation genes, such as NCBP3, NUDT4, CYFIP2, SNUPN, and EIF4E2, which were weakly expressed in most tumor tissues and highly expressed in normal tissues." (PMID 36226166, 2022). "The roles of NUDT4 and NUDT10 remain ambiguous in ccRCC tumor progression and metastasis." (PMID 37089261, 2023). "Our results showed that the relative expression of ENST00000413528 or lnc‐NUDT4‐4:1 was higher in tumor tissues than that in PTBE tissues (P < 0.05), while NONHSAT207178 and NONHSAT174301 were downregulated in tumor tissues (P < 0.05), all of which were consistent with the microarray results." (PMID 30924320, 2019).
cancer (9 papers, 2017 to 2025). A tumor composed of atypical neoplastic, often pleomorphic cells that invade other tissues. "The elevated NUDT4 expression levels in cancer cells increased the sensitivity to selumetinib, but drug resistance to everolimus was correlated with them." (PMID 37089261, 2023). "Studies have suggested that NUDT4 is significantly downregulated in various cancers, including KIRC, which matches our results." (PMID 37968670, 2023). "The results showed m7G methyltransferases, such as METTL1 and WDR4, were upregulated in a wide range of cancers, while RNA-binding and decapping enzymes (NUDT4, NUDT16, and NUDT10) were significantly downregulated." (PMID 35592316, 2022). "Although NUDT2 was overexpressed only in a subset of cancers, NUDT4 was downregulated in all cancers and appeared to be highly expressed throughout all normal tissues." (PMID 29142246, 2017). "However, the expression of CYFIP2, IFIT5, and NUDT4 were negatively correlated with the prognosis of most cancer patients." (PMID 36226166, 2022). "In our results, NUDT4 was related to poor survival, but little is known in cancer development." (PMID 36761423, 2022). "Compared to normal tissues, most genes were upregulated in cancer tissues, while EIF4E3, NUDT12, and NUDT4 were downregulated." (PMID 40018039, 2025). "To facilitate the clinical transformation of the five genes model, we further identified FDA-approved sensitive drugs that express high levels of CYFIP2, EIF4A1, NUDT1, NUDT4, and NUDT10 in multiple cancer cell types." (PMID 37089261, 2023).
heart disease (1 paper, 2021). "Further potentially disease-relevant protein candidates without a known functional relation to hypertrophy, fibrosis or decompensated heart disease were SLTM, HNRNPLL, FIP1L1, RNMT, KRT18 and PUF60 and the downregulated NUDT4, GCAT, KIDINS220 and ARVCF." (PMID 34937869, 2021).
NUDT4 also shares sentences with these, for which no sentence is quoted: infectious disease (1 paper); liver fibrosis (1); lung adenocarcinoma (1); mastitis (1); ovarian carcinoma (1).